TMEM161B (transmembrane protein 161B)
Description:
Essential for maintaining normal cardiac rhythm in the developing heart and for neonatal survival (By similarity). Inhibits potassium and calcium currents in the cardiomyocytes, this assists in timely action potential repolarization and thereby maintains normal cardiac rhythm (By similarity).
Synonyms: MGC33214; FLB3342; PRO1313
Tractability: Antibody: UniProt places it where antibodies can reach, with medium confidence; UniProt predicts a signal peptide or a membrane-spanning region; its Gene Ontology location is reachable by antibodies, with medium confidence. PROTAC: ubiquitination databases record sites on it.
Gene: Protein-coding gene on chromosome 5 (88,185,575 to 88,269,476, reverse strand). Ensembl gene ENSG00000164180.
Subcellular location: Cell membrane
Gene Ontology:
Biological process: regulation of cardiac muscle cell action potential; regulation of heart rate
Cellular component: plasma membrane
Genetic constraint (gnomAD): Loss-of-function variants: 25 observed, 44.19 expected, observed/expected ratio (o/e) 0.57, 90% interval 0.41 to 0.79. The upper end of that interval is the gene's LOEUF score, 0.79, which puts it in group 3 of 6, group 1 being the genes least tolerant of losing a copy. Missense variants: 356 observed, 461.94 expected, observed/expected ratio (o/e) 0.77, 90% interval 0.71 to 0.84. Synonymous variants: 138 observed, 165.9 expected, observed/expected ratio (o/e) 0.83, 90% interval 0.72 to 0.96.
Homologues: Orthologues: pig TMEM161B (97% identical), rabbit TMEM161B (97% identical), guinea pig TMEM161B (96% identical), mouse Tmem161b (95% identical), rat Tmem161b (95% identical), dog TMEM161B (93% identical), macaque TMEM161B (93% identical), chimpanzee TMEM161B (91% identical), tropical clawed frog tmem161b (84% identical), zebrafish tmem161b (76% identical), Drosophila melanogaster emei (43% identical), Caenorhabditis elegans Y87G2A.13 (27% identical). Paralogues in human: TMEM161A (48% identical).
Diseases named in the same sentence as TMEM161B in open-access papers:
TMEM161B is named in the same sentence as 15 diseases in open-access papers, as found by Europe PMC text mining. Sharing a sentence is not in itself a finding about the gene and the disease. The quoted sentences say what the papers report.
depression (4 papers, 2017 to 2023). "In our Australian sample of 3664 unrelated major depression cases and 7113 unrelated controls, SNP rs10514299 between TMEM161B and MEF2C and SNP rs11209948 near NEGR1 were nominally associated with major depression (P⩽0.05)." (PMID 28509901, 2017). "The 6 top blood biomarkers with the strongest overall CFE for tracking and predicting both depression and mania, hence bipolar mood disorders, after the first four steps were NRG1, DOCK10, GLS, PRPS1, TMEM161B, and SLC6A4." (PMID 33828235, 2021).
polymicrogyria (4 papers, 2023 to 2025). A developmental brain abnormality characterized by an excessive amount of small convolutions on the surface of the brain and cognitive dysfunction. "Exome sequencing of families with polymicrogyria (disordered cortical folding) revealed multiple individuals with biallelic deleterious variants in TMEM161B, which encodes a multi-pass transmembrane protein of unknown function." (PMID 36669111, 2023). "As part of a larger study using exome sequencing (ES) to study genetic causes of polymicrogyria (PMG), we discovered multiple families with segregating biallelic variants in TMEM161B." (PMID 36669111, 2023). "In addition to detecting pathogenic variants in genes previously linked to polymicrogyria (eg, ADGRG1/GPR56, SCN3A, TUBB2B), we discovered 6 genes linked to polymicrogyria for the first time (QRICH1, TMEM161B, PANX1, KIF26A, SCN2A, and MAN2C1)." (PMID 37486637, 2023).
holoprosencephaly (2 papers, 2023). Holoprosencephaly (HPE) is a complex brain malformation resulting from incomplete cleavage of the prosencephalon, occurring between the 18th and 28th day of gestation, and affecting both the forebrain and face, which results in neurological manifestations and facial anomalies of variable severity. "Complete loss of Tmem161b in mouse leads to a more severe earlier patterning phenotype—holoprosencephaly and spinal cord patterning defects consistent with loss of Shh signaling." (PMID 36669111, 2023). "Holoprosencephaly, in combination with the craniofacial and eye defects, suggest a failure in patterning related to Shh signaling, but unlike Shh KO mice, Tmem161b KO mice lacked other classic Shh or ciliopathy phenotypes, specifically outside of the CNS." (PMID 36669111, 2023). "Tmem161b null mice demonstrated holoprosencephaly, craniofacial midline defects, eye defects, and spinal cord patterning changes consistent with impaired Shh signaling, but were without limb defects, suggesting a CNS-specific role of Tmem161b." (PMID 36669111, 2023).
brain malformations (1 paper, 2023). "Homozygous or heterozygous missense mutations have also recently been reported for TMEM161B in patients with structural brain malformations, although its significance in the human heart remains to be determined." (PMID 37222785, 2023).
ciliopathy (1 paper, 2023). A genetic disorder of the cellular cilia or the cilia anchoring structures, the basal bodies, or of ciliary function. "Together, the gross phenotypes of the Tmem161b KO mouse imply a CNS-specific deficiency in normal Shh signaling, but no signs of Shh signaling defects or ciliopathy in tissues where developmental Tmem161b expression is low." (PMID 36669111, 2023). "On the other hand, the mouse null models, lacking Tmem161b function entirely, show manifestations of an early or more severe ciliopathy affecting overall forebrain patterning." (PMID 36669111, 2023).
Intellectual disability (1 paper, 2023). "The human syndrome caused by biallelic mutations in TMEM161B is stereotyped in its presentation of diffuse PMG, intellectual disability, and seizures with limited extra-CNS disease." (PMID 36669111, 2023).
TMEM161B also shares sentences with these, for which no sentence is quoted: Alzheimer disease (1 paper); brain disease (1); developmental and epileptic encephalopathy (1); dysplasia (1); glioma (1); mental disorder (1); microcephaly (1); Renal cyst (1); Ververi-Brady syndrome (1).